ERBB4 (erb-b2 receptor tyrosine kinase 4)
Diseases named in the same sentence as ERBB4 in open-access papers (continued):
Sharing a sentence is not in itself a finding about the gene and the disease.
liver cancer (3 papers, 2016 to 2023). An epithelial or non-epithelial malignant neoplasm that arises from the liver. "Downregulation of ERBB4 in tumors is in concordance with a well-established body of evidence on the roles of ERBB signaling as a tumor suppressor in liver cancer." (PMID 37985452, 2023). "Interestingly, in 50 pairs of liver cancer and its para-carcinoma tissues, there is significant negative correlation between ERBB4 and ACLY expression, which was consistent with our findings." (PMID 26701850, 2016).
mental disorder (3 papers, 2023 to 2024). A disease that has its basis in the disruption of mental process. "Other candidate genes, including ADCYAP1R1, NAP1L4, and ERBB4, have been reported in mental disorders." (PMID 37491364, 2023). "Stage T3 was also enriched for nervous system development (FDR = 6 × 10–12; e.g., ERBB4) and projection morphogenesis (FDR = 1 × 10–9; e.g., SEMA6D), and was most specifically marked by GRIA2, a glutamate ionotropic receptor subunit implicated in multiple mental disorders." (PMID 36865235, 2023).
metastatic cancer (3 papers, 2020 to 2022). A carcinoma which has spread from the original site of growth to another anatomic site. "NOTCH2, NOTCH2NL, KIF5B, and ERBB4 are highly expressed in primary cancer, while ERBB2, CLDN11 and CDK12 are overexpressed in metastatic cancer." (PMID 33441952, 2021). "Population-wide comparison between TT and LN single cells revealed that NOTCH2, NOTCH2NL, KIF5B, and ERBB4 are highly expressed in primary cancer, while CDK12, ERBB2, and CLDN11 are overexpressed in metastatic cancer." (PMID 33441952, 2021). "Note that subsite classification showed that in the TCGA-HNC dataset, besides oral cavity cancer, cancers of the laryngeal, oropharyngeal, and hypopharyngeal subsites also have Erbb4 mutations, but absent in MSK-IMPACT advanced/metastatic cancers of these subsites." (PMID 33053752, 2020).
nicotine addiction (3 papers, 2017 to 2024). "Using a Finnish twin family sample, we have previously detected association between nicotine dependence and ERBB4 (a neuregulin receptor), and linkage for smoking initiation at the ERBB4 locus on 2q33." (PMID 28892072, 2017). "Notably, ERBB4 have been linked to nicotine addiction as genome-wide association (GWA) and candidate gene studies for smoking behavior and nicotine dependence revealed that ERBB4 is a strong candidate for nicotine dependence, and several mutations were identified in addicted individuals." (PMID 38715099, 2024).
Papillary thyroid carcinoma (3 papers, 2013 to 2022). "ERBB3/ERBB4/RAF1 kinases were activated in papillary carcinoma compared to other variants, PAK3/PAK6/CDK1 kinases were activated in NOS, and PRKACA/PRKACB/PRKACG kinases were activated in differentiation variants." (PMID 35659036, 2022). "The results showed that papillary carcinoma was characterized by a low immune score, increased metabolism-related pathways, and the activated ERBB3/ERBB4 kinases." (PMID 35659036, 2022).
prostate tumor (3 papers, 2012 to 2022). "Indeed, the ErbB4 Q646C EGFP-TVV construct inhibited clonogenic proliferation of PC-3 or DU-145 human prostate tumor cell lines to almost the same extent as the untagged ErbB4 Q646C construct." (PMID 24791013, 2013). "Unfortunately, unlike the parental ErbB4 Q646C construct, the resulting ErbB4 Q646C EGFP construct fails to effectively inhibit clonogenic proliferation of PC-3 or DU-145 human prostate tumor cell lines." (PMID 24791013, 2013).
sarcoma (3 papers, 2016 to 2024). A usually aggressive malignant neoplasm of the soft tissue or bone. "DSRCT tumors did not have a significantly higher level of expression of ERBB3 or ERBB4 mRNA compared to the other sarcomas." (PMID 34841430, 2022).
Stroke (3 papers, 2016 to 2024). Sudden impairment of blood flow to a part of the brain due to occlusion or rupture of an artery to the brain. "Previous studies suggested that Nrg1 forward signaling via ErbB4 may aid recovery from stroke, a pathology associated with aging in humans." (PMID 31583038, 2019). "Neuroprotection in stroke by NRG-1 is mediated by erbB4 which physically associates with NIK." (PMID 27596278, 2016). "As previous studies indicated an increase in Nrg1 expression in response to hypoxia and that ErbB4 activation reduced ischemic infarct, we hypothesized that Nrg1 intracellular signaling might be neuroprotective in hypoxia and stroke." (PMID 31583038, 2019).
subarachnoid hemorrhage (3 papers, 2020 to 2025). A serious neurological disorder characterized by intracranial hemorrhage into the subarachnoid space. "ErbB4 is an epidermal growth factor receptor kinase which been shown to preserve BBB integrity after subarachnoid hemorrhage in rats." (PMID 33087130, 2020).
acute pancreatitis (2 papers, 2023 to 2025). An acute inflammatory process that leads to necrosis of the pancreatic parenchyma. "On the other hand, its activation could also be associated with a protective effect since ERBB4 phosphorylation plays a protective role in acute pancreatitis." (PMID 37341059, 2023). "Previous experiments have showed that overexpressing EGFR and ErbB4 protects mice from acute pancreatitis." (PMID 40702576, 2025).
anaplastic ependymoma (2 papers, 2023 to 2024). Anaplastic ependymoma is a rare, malignant type of ependymoma that most often arises in the supratentorial region of the brain of children and young adults and that manifests with variable symptoms including headaches, nausea, vision impairment, memory loss and difficulty walking. "In addition, the ERBB4 variant (rs839541) was reported in anaplastic ependymoma Grade III, and the KDR variant c.798+54G>A was reported in anaplastic ependymoma Grade III, ACP, and MPE tumors." (PMID 37273678, 2023).
anxiety disorder (2 papers, 2022 to 2024). A category of psychiatric disorders which are characterized by anxious feelings or fear often accompanied by physical symptoms associated with anxiety. "These evidence suggest that ErbB4 might be an important regulator of HPA axis activation and progression of anxiety disorders in ERβ-deficient mice treated with DSS." (PMID 36175956, 2022).
atrial fibrillation (2 papers, 2018 to 2021). A disorder characterized by an electrocardiographic finding of a supraventricular arrhythmia characterized by the replacement of consistent P waves by rapid oscillations or fibrillatory waves that vary in size, shape and timing and are accompanied by an irregular ventricular response. "Analysis of the reported AEs suggests that ibrutinib-associated atrial fibrillation is caused by binding to ERBB2/HER2 and ERBB4/HER4." (PMID 33777941, 2021).
biliary tract cancer (2 papers, 2023 to 2025). "Varlitinib is a reversible pan-HER inhibitor with nanomolar potency against ERBB4 and has shown efficacy in HER overexpressing biliary tract cancers." (PMID 41256885, 2025).
cardiomyopathy (2 papers, 2023 to 2025). A disease of the heart muscle or myocardium proper. "As expected, Erbb4 deletion resulted in a cardiomyopathy phenotype, with a significant increase in left ventricular internal diameter in diastole (LVIDd) and systole (LVIDs), and a fall in fractional shortening (FS)." (PMID 39794341, 2025).
childhood asthma (2 papers, 2013 to 2022). "We used an informative graph for oxidative stress derived from Gene Ontology and identified several variants in ERBB4, OXR1, and BCL2 with strong evidence for associations with childhood asthma." (PMID 24152222, 2013).
colon adenocarcinoma (2 papers, 2022 to 2024). "The expression level of ERBB4 in the tumor tissues of colon adenocarcinoma (COAD) and rectum adenocarcinoma (READ) was higher than the corresponding normal tissues." (PMID 38725859, 2024).
colorectal tumors (2 papers, 2006 to 2018). "In various types of cancer, including tumors of the head, neck, lung, and breast and colorectal tumors, the ErbB family of receptors (EGFR/HER1/ERBB1, HER2/neu/ERBB2, HER3/ERBB3, and HER4/ERBB4) is unregulated, producing an inappropriate cell stimulation." (PMID 30670929, 2018).
cyst (2 papers, 2023 to 2025). A sac-like closed membranous structure that may be empty or contain fluid or amorphous material. "In the ADPKD slices, phosphorylated EGFR was present at cyst lining epithelial cells of most cysts at the apical cell membrane, whereas phosphorylated ErbB2 was absent and phosphorylated ErbB4 was only present in some cysts (not shown)." (PMID 36914219, 2023).
developmental delay (2 papers, 2017 to 2021). "The phenotype of the patients with intronic ERBB4 deletions included developmental delay, ID, pulmonary stenosis, facial abnormality, polycystic kidney dysplasia and postaxial polydactyly." (PMID 33603162, 2021).
endometriosis (2 papers, 2017 to 2024). The growth of functional endometrial tissue in anatomic sites outside the uterine body. "Accordingly, further research is necessary to elucidate the role of NNMT and the ERBB4/PI3K/AKT signaling pathway in the pathophysiology of endometriosis." (PMID 39489776, 2024). "To date, few studies have addressed the role of ERBB4 in endometriosis." (PMID 39489776, 2024).
gastric adenocarcinoma (2 papers, 2016 to 2018). "Whether ERBB4 is indispensable for facilitating the peritoneal metastasis of gastric adenocarcinoma requires further investigation." (PMID 27270314, 2016).
Hodgkins lymphoma (2 papers, 2017 to 2019). A heterogeneous group of malignant lymphoid neoplasms of B-cell origin characterized histologically by the presence of Hodgkin and Reed-Sternberg (HRS) cells in the vast majority of cases. "Considering the shared awakening of ancient LTR promoters in HL and ERBB4 positive ALCL, it will be interesting to analyze ERBB4 expression in Hodgkin Lymphoma samples." (PMID 28061468, 2017).
Hypertension (2 papers, 2023 to 2025). The presence of chronic increased pressure in the systemic arterial system. "There was association with hypertension through inflammation (ERBB4) and oxidative stress and endothelial dysfunction (ERBB4 and RIPK2)." (PMID 40744952, 2025). "Indeed, chronic Ang II infusion markedly upregulated cardiac Erbb4-IR, which was associated with hypertension and development of hypertensive cardiac disease, as demonstrated by significant reductions in LVEF and LVFS and increases in LV mass and cardiac fibrosis." (PMID 37449045, 2023). "Targeting cardiac Erbb4-IR can effectively attenuate cardiac fibrosis in a mouse model of hypertension." (PMID 37449045, 2023). "Thus, this study aims to examine the role of Erbb4-IR for hypertensive heart disease by specifically silencing cardiac Erbb4-IR in a mouse model of Ang II-induced hypertension to determine its potential as a therapeutic target." (PMID 37449045, 2023). "In conclusion, this model supports that BTKi-induced AF or hypertension are rather derived from off-target effects partly mediated by TEC and ERBB4 for AF, and RIPK2 and ERRB4 for hypertension." (PMID 40744952, 2025). "Related to hypertension, common off-targets RIPK2 and ERBB4 were predicted to induce oxidative stress and endothelial dysfunction, and the latter also induced inflammation." (PMID 40744952, 2025).
idiopathic pulmonary fibrosis (2 papers, 2022 to 2023). Idiopathic pulmonary fibrosis (IPF) is a nonneoplastic pulmonary disease that is characterized by the formation of scar tissue within the lungs in the absence of any known cause. "Collectively, these results suggest that ERBB4 and SYK are attractive targets for IPF treatment; however, further preclinical studies are needed to confirm the suppression of lung fibrosis following the inhibition of the expression and activation of these kinases." (PMID 35130915, 2022).
lung squamous cell carcinoma (2 papers, 2022 to 2024). "Although systematic investigations are lacking to date, in a patient with a lung squamous cell carcinoma bearing a missense mutation in the ERBB4 gene (p.Arg847His), afatinib showed some efficacy, but the tumor also carried an EGFR amplification." (PMID 36476337, 2022).
memory impairment (2 papers, 2021 to 2022). "Altogether, the ErbB4 signaling pathway rises as a plausible mechanism by which neonatal HI results in deficits in hippocampal PV+ INs and memory impairments." (PMID 36613949, 2022).
mood disorder (2 papers, 2007 to 2021). A cognitive disorder a disturbance in which the person's mood is hypothesized to be the main underlying feature. "In this study, we have extended the concept of PV NRG1/ErbB4 signaling, cortical disinhibition and plasticity, which we and others have formulated in the visual cortex, to the mPFC, which is relevant for cognition and mood disorders." (PMID 33627623, 2021).
nasal polyp (2 papers, 2016 to 2020). "In nasal epithelium from nasal polyp patients, ErbB4 expression significantly increased compared to those from healthy subjects." (PMID 33217964, 2020). "An investigation using nasal epithelium from patients with nasal polyp showed that ErbB4 expression was localized in ciliated epithelial cells while EGFR was localized in p63+ basal cells." (PMID 33217964, 2020). "The current study investigates the expression profiles of EGF, EGFR and ERBB4 in patients with nasal polyps (NP), and their response to glucocorticosteroid (GC) treatment." (PMID 27285994, 2016).
Onset (2 papers, 2022 to 2025). The age group in which disease manifestations appear. "Additionally, studies have reported that over 70% of individuals with respiratory-onset ALS harbor ERBB4 insertions, compared to 25% in the general population, indicating that structural variations in ERBB4 may also influence the site of disease onset." (PMID 40469844, 2025).
ovarian serous carcinoma (2 papers, 2021 to 2022). "It was found that high-level ERBB4 expression was observed at a significantly higher frequency in ovarian serous carcinoma compared with normal control tissue, indicated that ERBB4 expression may correlate with chemotherapy-resistant ovarian serous carcinoma and shortened OS." (PMID 36185201, 2022).
psoriasis (2 papers, 2021 to 2024). An autoimmune condition characterized by red, well-delineated plaques with silvery scales that are usually on the extensor surfaces and scalp. "To explore the biological role and importance of ERBB4 in psoriasis development, we performed a loss-of-function assay by transfecting keratinocytes with ERBB4 siRNAs." (PMID 34667159, 2021). "Through gain-/loss-of-function and gene recovery assays, we proved that ERBB4 is functionally essential and responsible for the biological effects of miR-193b-3p on psoriasis development." (PMID 34667159, 2021). "Collectively, our findings reveal a link between miR-193b-3p deficiency and ERBB4 protein hyperactivation in psoriasis, which leads to abnormal proliferation and aberrant inflammation of keratinocytes, highlighting the potential use of miR-193b-3p as a novel therapeutic intervention for psoriasis." (PMID 34667159, 2021). "In conclusion, our results demonstrate that miR-193b-3p acts as a negative regulator of psoriasis pathogenesis by directly targeting ERBB4." (PMID 34667159, 2021). "In the IMQ-induced mouse model and lesional skin samples from psoriasis patients, ERBB4 protein levels were significantly upregulated." (PMID 34667159, 2021). "Strikingly, ERBB4 knockdown inhibited the expression of psoriasis-related genes and inflammatory genes in the presence or absence of M5 treatment." (PMID 34667159, 2021). "Mechanism study showed that ERBB4 is highly expressed in psoriasis patient’s epidermis and directly targeted by miR-193b-3p." (PMID 34667159, 2021). "However, further in vivo experiments and studies are needed to confirm the clinical value of miR-193b-3p and ERBB4 in psoriasis." (PMID 34667159, 2021). "However, the precise mechanism of ERBB4 regulating psoriasis pathogenesis needs more in vivo data and clinical evidence to elucidate." (PMID 34667159, 2021). "From the results above, we speculate that ERBB4 could promote the keratinocyte proliferation and inflammatory response through the STAT3 and NF-κB pathways, which might represent a novel role of ERBB4 in psoriasis pathogenesis." (PMID 34667159, 2021). "Furthermore, ERBB4 overexpression increased the expression of psoriasis-related genes and inflammatory genes, and the levels of phospho-STAT3 (Tyr705), phospho-STAT3 (Ser727), and phospho-NF-κB p65 (Ser311) in the presence or absence of M5 treatment." (PMID 34667159, 2021). "Strikingly, the protein levels of ERBB4, as well as STAT3 and NF-κB, were significantly upregulated in lesional skin samples from psoriasis patients." (PMID 34667159, 2021). "Interestingly, in nontransformed colonocytes, inflammatory cytokines (e.g., TNF-α) could induce strong ERBB4 expression through a mechanism involving NF-κB signaling, while both TNF-α and NF-κB play crucial roles in psoriasis pathogenesis." (PMID 34667159, 2021). "Moreover, the ERBB4 mRNA levels in the skin tissues derived from the healthy donors were not significantly different from those derived from psoriasis patients." (PMID 34667159, 2021). "However, the function of ERBB4 in psoriasis pathogenesis is not systematically studied." (PMID 34667159, 2021).
rectal cancer (2 papers, 2022 to 2025). A primary or metastatic malignant neoplasm that affects the rectum. "In rectal cancer, lncRNA EGOT enhanced radioresistance via miR-211-5p/ErbB4 axis." (PMID 35600868, 2022).
rectal tumors (2 papers, 2016 to 2022). "For example, although at low frequencies, we found that the PTEN gene was deleted, with a gradually increasing frequency from ascending tumors to the rectum, while both the deletion of SMAD4 and amplification of ERBB4 were enriched in descending or rectal tumors (P < 0.05)." (PMID 35487942, 2022).
renal cell carcinoma (2 papers, 2021). "Taken together, ERBB4 signaling adjacent to the T2DM and renal cell carcinogenetic mechanism subnetworks can be studied as potential promising targets and biomarkers for T2DM-associated renal cell carcinoma." (PMID 33801830, 2021).
synovial sarcoma (2 papers, 2016). "Of note, roneparstat inhibited ERBB4 activation as well as HB-EGF-induced Matrigel invasion also in the CME-1 synovial sarcoma cell line, which harbors a constitutively active receptor." (PMID 27374103, 2016).
thymic carcinoma (2 papers, 2017 to 2022). Thymic carcinoma (TC) is a type of thymic epithelial neoplasm characterized by a high malignant potential. "ERBB4 mutated thymic carcinoma might also be inhibited by EGFR family blockers such as lapatinib and afatinib." (PMID 27844328, 2017). "The receptor tyrosine kinases ALK and ERBB4, the serine/threonine kinase ATM, and the GTPase NRAS were mutated in one thymic carcinoma each." (PMID 27844328, 2017).
thyroid (2 papers, 2015 to 2018). "On the protein level, a tissue microarray study in proliferative thyroid lesions found a correlation of ERBB3 expression with LN metastasis whereas ERBB4 expression correlated with lower tumor stage." (PMID 25922907, 2015). "Two of these are EGFR (ERBB1) and ERBB4, which have not been previously reported to play a role in thyroid carcinogenesis." (PMID 29133385, 2018).
type 2 diabetic nephropathy (2 papers, 2023). "ERBB4 and its variants are associated with type 1 or type 2 diabetic nephropathy, polycystic ovary syndrome, obesity, hyperglycemia, hyperinsulinemia, and insulin resistance." (PMID 38149095, 2023). "Studies have shown that the ERBB4 variant rs7588550 can be significantly associated with the risk of type 1 and type 2 diabetic nephropathy by affecting the ERBB4 expression." (PMID 38149095, 2023). "Importantly, our recent study also found that the Erbb4-IR-miR-29b axis is a key mechanism of type 2 diabetic nephropathy because Erbb4-IR can bind the 3′ UTR of the miR-29b genomic sequence to suppress miR-29b expression at the transcriptional level." (PMID 37449045, 2023).